HNF1B (HNF1 homeobox B)
Diseases named in the same sentence as HNF1B in open-access papers (continued):
Sharing a sentence is not in itself a finding about the gene and the disease.
polycystic kidney disease (25 papers, 2012 to 2025). A usually autosomal dominant and less frequently autosomal recessive genetic disorder characterized by the presence of numerous cysts in the kidneys leading to end-stage renal failure. "The HNF1B gene [MIM 189907] that causes the phenotype similar to polycystic kidneys is transcription factor 2 located on chromosome 17q12." (PMID 31056860, 2019). "HNF-1β mutations have been associated with a variety of disorders of renal development with polycystic kidney disease." (PMID 24179489, 2013). "This would be similar to the kidney specific hnf1b manipulation in mice that leads to polycystic kidneys and to mutation of the hnf1b gene in zebrafish that is reflected in kidney defects, especially the formation of cysts." (PMID 22438943, 2012). "In this study, we observed that the ultrasound phenotypes of a fetus with HNF1B mutation included hyperechoic kidney and polycystic kidney, whereas the ultrasound phenotypes of the fetus with NPHP3 and KMT2D gene mutations included hyperechoic kidney and abnormal nervous system structure." (PMID 40909434, 2025). "Additionally, GANAB and HNF1β mutations may lead to mild polycystic kidney disease." (PMID 40507770, 2025). "Mutations in the HNF1β/TCF2 gene cause prenatal hyperechogenic kidneys and Potter’s sequence, as well as enlarged polycystic kidneys that can be confused with ARPKD." (PMID 34204582, 2021). "For polycystic kidney disease, the testing approach should be able to detect copy-number variations (CNVs) such as heterozygous deletions (e.g., in HNF1B) and to cover even complex genomic regions such as the PKD1 gene." (PMID 29479522, 2017). "For a direct role in the transcription of PKD2 and PKHD1, HNF1β has been recognized as a modifier in PKD, although mutations in HNF1B do not cause typical polycystic kidney disease." (PMID 33809516, 2021). "Large polycystic kidneys are also found in ARPKD as well as the much less common tumor-associated syndromes (tuberous sclerosis, Von Hippel–Lindau disease, Birt–Hogg–Dubé syndrome) and HNF1b-associated kidney disease." (PMID 29623269, 2018). "Since the majority of patients had targeted HNF1B testing, we may not eliminate the possibility of the presence of other gene mutations responsible for polycystic kidney disease or CAKUT." (PMID 38196016, 2024). "While many of these fetuses display normal-sized kidneys often with bilateral cortical cysts and normal amniotic fluid volume, HNF1β patients may also show Potter’s sequence with oligo-/anhydramnios and massively enlarged polycystic kidneys (>+3 SD) that mimic ARPKD." (PMID 29479522, 2017). "Samples of 111 individuals were available, displaying one of the following renal ciliopathy phenotypes: polycystic kidney disease (ARPKD/ADPKD), nephronophthisis (NPH) or nephronophthisis related ciliopathies (NPH-RC), Bardet-Biedl Syndrome (BBS), and HNF1B nephropathy (HNF1B)." (PMID 39098869, 2024). "For genetic workup, further polycystic kidney disease genes were analyzed, PKD1 and PKD2 in 12, HNF1B in 8, and DZIP1L and GANAB in 5 children each without detection of variants." (PMID 35812281, 2022).
endometrial cancer (24 papers, 2012 to 2024). Primary or metastatic malignant neoplasm involving the endometrium (mucous membrane that lines the endometrial cavity). "Seven cases and three controls had CNVs that colocalised with two endometrial cancer risk SNPs (rs11263763 and rs11651052) located in intron 1 of HNF1B." (PMID 39495297, 2024). "GGG haplotypic structure of rs4430796‐rs11651052‐rs11263763 variants with 5 kb distance on HNF1B gene is associated with prostate and endometrial cancers in European population." (PMID 39031745, 2024). "Other identified transcription factors have also been reported to be associated with tumors, such as FOXA2 in oral cancer and endometrial cancers, HNF1B in prostate cancer." (PMID 36456645, 2022). "In the genome-wide association study of endometrial cancer, the susceptibility locus close to HNF1B on chromosome 17q was associated with endometrial cancer." (PMID 33397383, 2021). "The associations between endometrial cancer and variants in or around HNF1B, CYP19A1, SOX4, MYC, KLF and EIF2AK found in earlier GWAS were then replicated in the latest and largest GWAS." (PMID 32066633, 2020). "Our study summarizes the evidence and helps to reveal that common variants of HNF1B are associated with risk of prostate and endometrial cancer." (PMID 30053805, 2018). "Given the relevance of HNF1B variants to cancer biology, we attempted to estimate the strength of the genetic associations between these variants and prostate and endometrial cancers." (PMID 30053805, 2018). "Two publications were included in the evaluation of the association between the HNF1B rs4430796 A > G and endometrial cancer." (PMID 30053805, 2018). "Two publications were included in the analysis of the association between the HNF1B rs7501939 and endometrial cancer." (PMID 30053805, 2018). "Fine-mapping studies of the PRCA risk locus near HNF1B have indicated potentially multiple variants independently contributing to disease susceptibility for prostate and endometrial cancers." (PMID 29156765, 2017). "Our findings provide evidence for a single signal associated with endometrial cancer risk at the HNF1B locus, and that risk is likely mediated via altered HNF1B gene expression." (PMID 25378557, 2015). "We previously found single-nucleotide polymorphisms (SNPs) at the HNF1B locus to be associated with endometrial cancer, and now report extensive fine-mapping and in silico and laboratory analyses of this locus." (PMID 25378557, 2015). "Genome-wide association studies (GWAS) have also been used to dissect the genetics of endometrial cancer and so far have convincingly identified one associated SNP, rs4430796, on chromosome 17q close to the HNF1B gene." (PMID 25487306, 2015). "SNP rs4430796 was identified as an endometrial cancer susceptibility locus close to HNF1β on chromosome 17q." (PMID 26464794, 2015). "The most significantly associated SNP was rs4430796 located in HNF1B intron 2, with the minor ‘G’ allele protective for endometrial cancer." (PMID 25378557, 2015). "We have previously identified single-nucleotide polymorphisms (SNPs) associated with endometrial cancer risk at the hepatocyte nuclear factor 1 homeobox B (HNF1B) locus using a genome-wide association study (GWAS) approach." (PMID 25378557, 2015). "The HNF1β SNPs (rs4430796 and rs7501939) were associated with endometrial cancer risk in two independent studies and that the associations were observed across multiple racial/ethnic groups." (PMID 26464794, 2015). "Our results provide evidence for a single signal associated with endometrial cancer risk at the HNF1B locus, and that risk is likely mediated via altered HNF1B gene expression." (PMID 25378557, 2015). "A genome-wide association study has linked minor alleles of certain single nucleotide polymorphisms in HNF1B with a decreased risk of endometrial cancer." (PMID 26487094, 2015).
endometrial cancer (continued). "Fine-mapping of the multi-cancer HNF1B locus on chromosome 17q12 has revealed the presence of one multivariant haplotype associated with the risk of endometrial cancer." (PMID 25378557, 2015). "A close association between rs4430796 polymorphism of HNF1B gene and decreased endometrial cancer (EC) risk has been demonstrated." (PMID 25885815, 2015). "A genome-wide association study identified single nucleotide polymorphisms in HNF1β associated with endometrial cancer risk in women of European background." (PMID 26464794, 2015). "In conclusion, HNF1B SNPs are associated with risk of endometrial cancer and that the associated relative risks are similar for Type I and Type II tumors." (PMID 22299039, 2012). "A recent genome-wide association study (GWAS) identified common single nucleotide polymorphisms (SNPs) in HNF1B associated with endometrial cancer risk in women of European background." (PMID 22299039, 2012). "We show that the HNF1B SNPs (rs4430796 and rs7501939) identified in a recent endometrial cancer GWAS are associated with endometrial cancer risk in two independent studies and that the associations were observed across multiple racial/ethnic groups." (PMID 22299039, 2012). "We also examined the associations between HNF1B and endometrial cancer across racial/ethnic groups and tumor histological types, and effect modification by known endometrial cancer risk factors." (PMID 22299039, 2012). "Association between HNF1B variants and Type I and Type II endometrial cancer." (PMID 22299039, 2012). "Our findings establish the subtypes of endometrial cancer occurring in the Nurses' Health Study, corroborate the sensitivity of certain well-established biomarkers, and call into question previously identified associations between certain biomarkers (e.g., HNF1B) and particular histotypes." (PMID 33986807, 2021). "To provide a synopsis of the current understanding of the association between variants of HNF1B and cancer susceptibility, we conducted a comprehensive research synopsis and meta-analysis to evaluate associations between HNF1B variants and prostate and endometrial cancers." (PMID 30053805, 2018). "We found that single nucleotide polymorphisms (SNPs) in HNF1B, KLF, EIF2AK, CYP19A1, SOX4 and MYC were strongly associated with incident endometrial cancer." (PMID 32066633, 2020). "Three HNF1B isoforms were measured by TCGA, the presence of which was confirmed by our own mRNA analysis of endometrial cancer cell lines: isoform A (uc010wdi.1), isoform B (uc002hok.3) and isoform C (uc010cve.1)." (PMID 25378557, 2015). "Furthermore, CNVs overlapping HNF1B were more than six times as frequent in endometrial cancer cases compared to controls (OR = 7.59, 95% CI = 2.29–28.99, p = 0.001)." (PMID 39495297, 2024). "Here, we report the fine-scale mapping of the HNF1B locus incorporating data for 1184 genotyped and imputed SNPs in 6608 endometrial cancer cases and 37 925 controls of European ancestry, and analyses aimed at exploring the function of the most likely causal variants." (PMID 25378557, 2015). "In summary, we provide additional evidence that HNF1B is involved in endometrial cancer etiology." (PMID 22299039, 2012). "We observed significant associations between HNF1B variants and endometrial cancer only among non-diabetics in both studies." (PMID 22299039, 2012). "Our study results also suggest that HNF1B plays an important role in prostate and endometrial cancers, and these variations may serve as efficient and economical biomarkers for the diagnosis of prostate and endometrial cancers." (PMID 30053805, 2018). "Thus far, only one GWAS endometrial cancer risk locus has been identified [HNF1 homeobox B (HNF1B)] that is independent of BMI and has been replicated in independent populations of European and non-European descent." (PMID 26606540, 2015).
endometrial cancer (continued). "The gene expression results showed that HNF1B gene expression is significantly different from adjacent normal tissues in endometrial cancer." (PMID 39031745, 2024). "Similar findings in a small study of 33 endometrial carcinomas showed that all CCCs were positive for HNF1β and all non-CCCs were negative." (PMID 37383161, 2023). "In addition, the results also revealed a positive correlation between HNF1B expression and myeloid DC infiltration levels in liver hepatocellular carcinoma (LIHC, r= 0.358, p = 7.29e-12), Uterine Corpus Endometrial Carcinoma (UCEC, r=0.289, p=6.32e-03)." (PMID 33173410, 2020). "However, not only did HNF1B stain ovarian CCC, but expression was also detected in other tumors with cytoplasmic clearing, including renal CCC, endometrial carcinoma, germ cell tumors with yolk sac elements, and ovarian and endometrial carcinomas with mixed histology." (PMID 24040285, 2013).
hepatocellular carcinoma (20 papers, 2007 to 2025). A malignant tumor that arises from hepatocytes. "Down-regulation of HNF1B is associated with progression of hepatocellular carcinomas, and indicates poor prognosis of renal and prostate carcinomas." (PMID 25378557, 2015). "HNF1β has been demonstrated to be associated with the risk of hepatocellular carcinoma (HCC)." (PMID 26464794, 2015). "HNF1B somatic mutations were observed in several human cancers, among which hepatocellular carcinoma (HCC), confirming further, as previously discussed, its role as an oncogene/tumor suppressor gene." (PMID 36672242, 2023). "In fact, the knockdown of both Hnf-1α and Hnf-1β decreased the expression of Angptl8 protein in both mouse hepatoma cells and mouse primary hepatocytes." (PMID 32561878, 2020). "Combinatorial analyses of H3K36me3 expression with CK19 expression or HNF1β expression in the tumor progression of hepatocellular carcinoma." (PMID 30356299, 2018). "Combinatorial analysis of H3K36me3 signature enrichment, CK19 expression and HNF1β expression in the tumor progression of hepatocellular carcinoma." (PMID 30356299, 2018). "HNF1β is upregulated in hepatocellular carcinoma (HCC), and high level of HNF1β leads to poor overall survival." (PMID 28219405, 2017). "We retrospectively investigated the expression of HNF-1β in 90 patients with hepatocellular carcinoma and found that the high expression of HNF-1β indicated poor prognosis." (PMID 28684878, 2017). "Studies showed that cultured cells derived from differentiated hepatoma cells express HNF1α, whereas cultured dedifferentiated hepatoma cells express HNF1β instead of HNF1α." (PMID 26464794, 2015). "Other genes like HNF1, insulin‐like growth factor binding protein 1, Albumin, α‐fetoprotein were downregulated in mouse hepatoma cells on suppression of HNF1B by RNAi, whereas apolipoprotein, α1‐antitrypsin, alcohol dehydrogenase 2 and α‐fibrinogen showed increased expression." (PMID 33580750, 2021). "Another clinicopathological study showed that the HNF1B expression in hepatocellular carcinoma may be related with the change of phenotype on recurrence." (PMID 33173410, 2020). "In human hepatoma cells, HNF4α has been suggested to be directly regulated by HNF1β." (PMID 26464794, 2015). "On the contrary, the high expression of HNF1β enhances the tumor-forming ability of HCC cells in vivo, and promotes the dedifferentiation of hepatocellular carcinoma cells into liver cancer stem cells by activating Notch signal pathway, as well as the invasion of HCC cells and the occurrence of EMT." (PMID 35096588, 2021). "HNF-1B was completely negative in all colorectal cancer, breast cancer, hepatocellular carcinoma, and lung squamous cell carcinoma." (PMID 30065837, 2018). "The aim of this study was to examine the expression of HNF-1B in different pathologic subtypes of primary liver cancer, including hepatocellular carcinoma (HCC) and cholangiocarcinoma (ICC), and the relationship between HNF-1B expression, clinicopathological features and prognosis." (PMID 26311117, 2015). "HL secretion was only observed with hepatoma cell lines that express HNF1α or HNF1β mRNA, but not all cell lines with detectable HNF1α or -β expression do also secrete HL." (PMID 17428321, 2007).
pancreatic cancer (20 papers, 2006 to 2024). "A chromatin accessibility signature and associated transcriptional factors (ZKSCAN1 and HNF1β) are significantly correlated with pancreatic cancer prognosis." (PMID 36546899, 2022). "Interestingly, a recent study showed that mutated KRAS can induce abnormal regulations of pancreatic transcription factors including HNF-1B, which in turn causes abnormal cell growth and proliferation that leads to pancreatic cancer." (PMID 30065837, 2018). "The role of HNF1B in pancreatic cancer development was mainly related to tumor suppressor functions." (PMID 36672242, 2023). "HNF1B expression seems to play an important role in KRAS activation for pancreatic tumour, highlighting the need for additional studies to develop therapeutic strategies improving survival in PDAC (pancreatic ductal adenocarcinoma) patients." (PMID 33580750, 2021). "Epigenetic inactivation of HNF1B is seen in serous ovarian tumors, and has been detected in ovarian, colorectal, gastric and pancreatic cancer cell lines, suggesting that HNF1B promoter hypermethylation can be a feature of tumorigenesis." (PMID 25378557, 2015). "Epigenetic inactivation of HNF1β is also seen in colorectal, gastric, and pancreatic cancer cell lines, suggesting involvement of epigenetic inactivation of HNF1β in tumorigenesis." (PMID 26464794, 2015). "High expression of HNF1β showed worse survival in both pancreatic carcinoma and hepatocelullar carcinoma." (PMID 26464794, 2015). "This study identifies HNF1B as a potential tumour suppressor gene in pancreatic cancer." (PMID 33580750, 2021). "However, no variants of HNF1B have been hitherto associated with an increased risk of pancreatic cancer development." (PMID 36672242, 2023). "Also, HNF1β expression is increased in human pancreatic cancer and predicts poor survival." (PMID 28219405, 2017). "IPF1/PDX1 regulates downstream molecules such as Neurogenin 3 (NGN3), Forkhead Box A2 (FOXA2), Hepatocyte Nuclear Factor 1 Beta (HNF1B), Fibroblast Growth Factor Receptor 2 (FGFR2IIIB), and Spondin 1, which are involved in pancreatic development, differentiation, and function in pancreatic cancer." (PMID 39239563, 2024).